GTF2A1L (general transcription factor IIA subunit 1 like)
Description:
May function as a testis specific transcription factor. Binds DNA in conjunction with GTF2A2 and TBP (the TATA-binding protein) and together with GTF2A2, allows mRNA transcription.
Synonyms: ALF
Tractability: No criterion of Open Targets' tractability assessment is met for any kind of drug.
Gene: Protein-coding gene on chromosome 2 (48,617,798 to 48,733,148, forward strand). Ensembl gene ENSG00000242441.
Subcellular location: Nucleus
Subcellular location (Human Protein Atlas): Nucleoplasm; Cytosol
Gene Ontology:
Molecular function: protein binding; transcription coactivator activity
Biological process: cognition; transcription by RNA polymerase II; positive regulation of DNA-templated transcription; transcription initiation at RNA polymerase II promoter
Cellular component: nucleoplasm; transcription factor TFIIA complex; cytoplasm; nucleus
Genetic constraint (gnomAD): Loss-of-function variants: 42 observed, 44.53 expected, observed/expected ratio (o/e) 0.94, 90% interval 0.74 to 1.22. The synonymous counts are far from expectation, so gnomAD's model fits this gene poorly and the ratio says little. Missense variants: 697 observed, 543.52 expected, observed/expected ratio (o/e) 1.28, 90% interval 1.2 to 1.37. Synonymous variants: 234 observed, 184.39 expected, observed/expected ratio (o/e) 1.27, 90% interval 1.14 to 1.41.
Homologues: Orthologues: dog GTF2A1L (84% identical), pig GTF2A1L (83% identical), rabbit GTF2A1L (77% identical), rat Gtf2a1l (73% identical), mouse Gtf2a1l (71% identical), guinea pig GTF2A1L (69% identical), tropical clawed frog gtf2a1l (48% identical), zebrafish gtf2a1l (35% identical), Drosophila melanogaster TfIIA-L (24% identical), Caenorhabditis elegans pqn-51 (20% identical). Paralogues in human: GTF2A1 (28% identical).
Diseases named in the same sentence as GTF2A1L in open-access papers:
GTF2A1L is named in the same sentence as 12 diseases in open-access papers, as found by Europe PMC text mining. Sharing a sentence is not in itself a finding about the gene and the disease. The quoted sentences say what the papers report.
bladder cancer (1 paper, 2024). "The GTF2A1L gene is cancer-significant, and there are materials on the relationship of its expression with such oncological diseases as breast angiosarcoma, endometrial carcinoma, bladder cancer, and medulloblastoma in children." (PMID 38672173, 2024).
GTF2A1L also shares sentences with these, for which no sentence is quoted: breast angiosarcoma (1 paper); cancer (1); cervical cancer (1); colorectal cancer (1); endometrial carcinoma (1); endometriosis (1); heart failure (1); liver carcinoma (1); medulloblastoma (1); ovarian carcinoma (1); polycystic ovaries (1).